NFKB1 (nuclear factor kappa B subunit 1)
Diseases named in the same sentence as NFKB1 in open-access papers (continued):
Sharing a sentence is not in itself a finding about the gene and the disease.
viral infection (983 papers, 2004 to 2026). "The generation of pro-inflammatory miR-146a-5p was activated upon activation of NFKB1 in neural cells, which played essential roles in the course of neurological disorders in the context of viral infections." (PMID 40673003, 2025). "These MKs carry type I IFN and inflammatory genes and show an upregulation of genes conditioned by NFKB1, characteristics of a response to viral infection including that to SARS-CoV-2." (PMID 35708858, 2022). "Among the increased transcription factor IRFs, STATs, MYC, NFKB1, NFKB2, and NF-kappa B RELA have been implicated in viral infection." (PMID 34940755, 2021). "Collectively, these results indicate that the c-Myc and Nfkb1 transcriptional regulation of costimulatory signals is likely to modulate the generation of virus-specific memory CD8+ T cells to viral infection." (PMID 26791245, 2016). "Here, we demonstrated that the defective development of memory CD8+ T cells in Cd28−/− or Ox40−/− mice was caused by the reduced expression of two transcriptional factors c-Myc and Nfkb1 during viral infection." (PMID 26791245, 2016). "In contrast to IKAROS defects but similar to cytotoxic T lymphocyte–associated protein 4 (CTLA4) haploinsufficiency, we observed that NFKB1 haploinsufficiency can also result in chronic and severe viral disease, as noted for cytomegalovirus and JC virus infections in 3 of our patients." (PMID 29477724, 2018). "NFKB1 has described links with allergy or inflammation and may even describe the well-established relationship between viral infections and allergic exacerbations or allergy development." (PMID 28729650, 2017). "A viral infection is envisioned to interact with predisposition networks which include counterpart proteins in various downstream stages (including in the current data set: FOS, ELAVL1, NFkB1, POLR3B, and others at different cellular compartments and stages of the tumorigenesis)." (PMID 26442106, 2015). "The polymorphism of NFKB1 may affect the susceptibility to these viral infections-related malignancies; however, due to the lack of patients’ detail history of infections, the results in this study may be limited." (PMID 23457512, 2013). "The influence of EGb on inflammatory-associated genes expression that regulate innate immune response to viral infection and cytokine production, namely IRF-3, IRF-7, tetherin, SOCS1, SOCS3, NFKB1, p65, and MxA was also examined." (PMID 35631163, 2022). "The map illustrates that HSPA8 and proteins in subnetworks, such as EIF2AK3, TLR4, NFKB1, BAK1, and RelA, are enriched in viral infection of several viruses." (PMID 34769416, 2021). "In summary, we provide evidence that the transcriptional regulation of c-Myc, together with Nfkb1 from CD28 or TNF family members, controls the development of memory CD8+ T cells during viral infection." (PMID 26791245, 2016). "Besides, genetic defects in some molecules that interact with T cells (such as NFKB1, NFKB2, and TNFRSF13B) in patients diagnosed with CVID can also lead to critical viral diseases." (PMID 40442532, 2025). "As for DDX58, NFκB1, TOLLIP, RIPK1, DDX3Y, TRIM25 and JAK2, which are involved in antiviral signalling transduction, both increased mRNA abundance and switched poly(A) sites eventually led to enhanced protein production following viral infection." (PMID 28233779, 2017). "However, on day 20 p.i., the levels of these cytokines were significantly higher in D2.129P2 (B6)-Nfκb1 homozygote mice than in D2.129P2 (B6)-Nfκb1 wild-type mice (p < 0.05), indicating a lack of clearance of viral infection, such as C. rodentium infection." (PMID 35740465, 2022).
lung carcinoma (947 papers, 2005 to 2026). "The stratified association between the NFKB1 polymorphism and lung cancer risk according to gender and smoking status is shown in Table-V." (PMID 26870106, 2015). "By using ins/ins genotype as the reference, the heterozygous and homozygous variant genotypes of the NFKB1 polymorphism were found to be significantly associated with the reduced risk of lung cancer(P=0.002 for heterozygous, P<0.001 for variant)." (PMID 26870106, 2015). "Polymorphisms in NFKB1 and NFKBIAgenes were associated with risk of lung cancer." (PMID 26870106, 2015). "FOXM1 is required for the Kras-induced formation of lung cancer by activating genes critical for the nuclear factor-kB (NF-kB) and c-Jun N-terminal kinase (JNK) pathways, such as Ikbkb, Nfkb1, Nfkb2, Rela, Jnk1, N-Myc, Pttg1 and Cdkn2a." (PMID 30992007, 2019). "Following the observation that Tpl2 expression was also decreased in a NFKB1−/− human lung cancer cell line, Fan Sun and colleagues demonstrated that re-expressing p105, and not p50, restored Tpl2 levels in these cells, resulting in reduced tumour growth." (PMID 30205516, 2018). "Association between combinations of NFKB1 -94 ins/del ATTG polymorphism and NFKBIA -826C>T polymorphism and lung cancer risk." (PMID 26870106, 2015). "Association between NFKB1 -94 ins/del ATTG polymorphism, NFKBIA -826C>Tpolymorphism and NFKBIA -881A>G polymorphism and lung cancer risk." (PMID 26870106, 2015). "Association between combinations of NFKB1 -94 ins/del ATTG polymorphism and NFKBIA -881A>G polymorphism and lung cancer risk." (PMID 26870106, 2015). "Association between NFKB1 -94 ins/del ATTG polymorphism and lung cancer risk according to sex and smoking status." (PMID 26870106, 2015). "Association between combinations of NFKB1 -94 ins/del ATTG polymorphism and NFKBIA -881A>G polymorphism and lung cancer risk is shown in Table-III." (PMID 26870106, 2015). "The association of combinations of NFKB1 -94 ins/del ATTG polymorphism and NFKBIA -826C>T polymorphism with lung cancer risk is shown in Table-II." (PMID 26870106, 2015). "To test our hypothesis, we conducted a case-control study to investigate the association of NFKB1 -94 ins/del ATTG polymorphism and NFKBIA -826C>T and -881A>G polymorphisms with the risk of lung cancer in a Chinese population." (PMID 26870106, 2015). "We have showed that the variant alleles of NFKB1 -94 ins/del ATTG polymorphism, NFKBIA -826C>T polymorphism and NFKBIA -881A>G polymorphism could influence the risk of lung cancer in China." (PMID 26870106, 2015). "The association between NFKB1 and NFKBIA polymorphisms and lung cancer risk is shown in Table-I." (PMID 26870106, 2015). "In this study, we also investigated the correlations between 35 polymorphisms in 9 DNA repair genes (XRCC3, BRCA2/ZAR1L, XPC, RAD52, MAD2L2, NFKB1, NFKBIA, TNFRSF1A, and FASN) with platinum-based chemotherapy prognosis in 399 patients with lung cancer." (PMID 35899106, 2022). "Cytotoxicity studies in four lung cancer cell lines were complemented with measurement of gene expression of apoptosis-related proteins Bcl-2, BAX and the pro-survival proteins NFκB-1 and COX-2, as well as quantification of caspase activity." (PMID 26861394, 2016). "Here we studied the cytotoxic properties of s-cal14.1a in four lung cancer cell lines, we quantified the expression of genes involved in execution and regulation of apoptosis namely Bcl-2, BAX and the pro-survival proteins NFκB-1 and COX-2, we also analyzed caspase activity." (PMID 26861394, 2016).
prostate carcinoma (934 papers, 2003 to 2026). A carcinoma that arises from epithelial cells of the prostate gland. "The NFKB1 -94 polymorphism was shown to decrease prostate cancer risk in both heterozygous and homozygous comparison models (odds ratios of 0.74 (95% CI = 0.58–0.96) (P = 0.02) and 0.57 (95% CI = 0.42–0.78) (P < 0.01), resp)." (PMID 26788504, 2015). "This risk reduction was in agreement with an in vitro assay which showed that the del allele decreased the transcriptional activity of NFKB1, thereby truncating its role in promoting inflammation, which in turn led to the decreased prostate cancer risk." (PMID 26788504, 2015). "For NFKB1-94 ins/del polymorphism, a significantly decreased prostate cancer risk was observed in the heterozygous comparison model (ins/del versus ins/ins) and homozygous comparison model (del/del versus ins/ins)." (PMID 26788504, 2015). "The -94 ins/del ATTG polymorphism (rs28362491) in NFKB1 promoter reportedly elicits a regulatory effect on the NFKB1 gene and plays a role in the susceptibility of individuals to various malignancies, including gastric cancer, ovarian cancer, prostate cancer, and oral squamous cell carcinoma." (PMID 23977085, 2013). "We observed that the NFKB1-94 ins/del polymorphism was associated with decreased risk of prostate cancer in both heterozygous and homozygous comparison models, suggesting that the variant del allele may be linked to a reduced inflammatory status among its carriers and, therefore, a reduced risk." (PMID 26788504, 2015). "In advanced prostate cancer, elevated NAIP is an early event, and its cytoprotective effects are associated with the NFkB-1 transcription factor signaling pathway." (PMID 31269724, 2019). "Birnie and colleagues identified genes with altered expression in prostate cancer stem cell population such as NFKB1 and IL6." (PMID 31083587, 2019). "The effect of interactions between polymorphisms in related genes (NFKB1 and NFKBIA; COX-2 and COX-1) on the risk of prostate cancer was also examined." (PMID 26788504, 2015). "We aimed to examine the association between PPARG Pro12Ala, NFKB1 -94 ins/del, NFKBIA -826C/T, COX-1 (50C>T), and COX-2 (-1195G>A) polymorphisms on prostate cancer risk." (PMID 26788504, 2015). "In vitro studies showed that the isolated chalcone cardamonin inhibited prostate cancer cell proliferation and decreased the expression of NFkB1." (PMID 24514747, 2014). "However, NFKB1 protein expression progressively increased in normal, benign prostatic hyperplasia and prostate cancer tissues." (PMID 26683658, 2015). "In conclusion, NFKB1 -94 ins/del and COX-2 (-1195G>A) polymorphisms may be, respectively, associated with decreased and increased prostate cancer risk in the Chinese population." (PMID 26788504, 2015). "In this study, we investigated and established the association of five inflammation-related genetic polymorphisms, namely, PPARG Pro12Ala, NFKB1-94 ins/del, NFKBIA-826C/T, COX-1 (50C>T), and COX-2 (-1195G>A) polymorphisms, with prostate cancer risk in a Chinese population." (PMID 26788504, 2015). "Moreover, in prostate cancer, EZH2 can repress the expression of tumor suppressors such as DAB2IP, p16 (CDKN2A), CDK4, E-cadherin (CDH1), MSMB, Ras (KRAS), NF-κB (NFKB1), EMT regulator." (PMID 27835578, 2016). "Taken together, our findings identified a STAT1/lactate/NFκB1/MCP-1 positive feedback mechanism as a driver of prostate cancer progression and resistance to radiotherapy that functioned by interaction to macrophages, which could be potential therapeutic targets for the advanced prostate cancer." (PMID 41856970, 2026). "NFKB1 (nuclear factor-κB subunit 1) and NFKB2 (nuclear factor-κB subunit 2) gene expression was up-regulated by Ang1–7 in all prostate cancer cells, but this increase was not statistically significant for the DU-145 line." (PMID 30361641, 2018).
colorectal cancer (879 papers, 2003 to 2026). A primary or metastatic malignant neoplasm that affects the colon or rectum. "NFKB1 is involved in the regulation of tumor-associated macrophage polarization in colorectal cancer." (PMID 37954130, 2023). "SNP rs2228991 in REST, a gene in non-neuronal tissues encoding a transcription factor binding to the silencer of neuronal genes, was reported to be associated with an increased risk of colorectal cancer when combined with SNPs in the NFKB1 gene." (PMID 36292186, 2022). "As for rs3747811 (IKBKB), it has not been yet investigated in previous studies for its involvement in the development of obesity-related phenotypes, and was only found to decrease the risk of colorectal cancer combined with rs4648110 (NFKB1)." (PMID 30886629, 2019). "Distribution of genotypes in NFκB1 and NFκBIA, and results of logistic regression analysis for associations with risk of colorectal cancer." (PMID 21738780, 2011). "While the importance of the genes in the inflammation pathway has been well documented, our study is the first to comprehensively examine polymorphisms in either NFKB1 or IKBKB to identify functional polymorphisms associated with colorectal cancer." (PMID 21129206, 2010). "We applied the hapConstructor method to a multilocus investigation of candidate genes involved in pro-inflammatory cytokine IL6 production, IKBKB, IL6, and NFKB1 (16 SNPs total) hypothesized to operate together to alter colorectal cancer risk." (PMID 21129206, 2010). "Therefore, we hypothesized that the NFκB1 (-94del/insATTG) and NFκBIA (2758 A>G) polymorphisms were associated with colorectal cancer (CRC) susceptibility." (PMID 21738780, 2011). "Allicin, also, increases the sensitivity of colorectal cancer cells to radiation through the inhibition of a NFKB1-mediated pathway." (PMID 34422220, 2021). "Evaluation of the differential expression between carcinoma and normal mucosa showed that SMAD3 rs12708491 and rs2414937, NFκB1 rs230510 and rs3821958, and RUNX3 rs6672420 were associated with several miRNAs for colorectal carcinoma." (PMID 28061442, 2017). "In cancer type subgroup analysis, NFKB1 −94ins/delATTG polymorphism still failed to impact the susceptibility in subgroup of colorectal cancer, gastric cancer and oesophageal cancer." (PMID 34672421, 2021). "The NFKB1 and NFKBIA genes, located on chromosome 4q24 and 14q13, respectively, are associated with the development of cancers, including oral cancer (OC), gastric cancer, colorectal cancer, and Hodgkin's lymphoma." (PMID 31612070, 2019). "Other genes, such as nuclear factor kappa B1 (NFκB1), mammalian target of rapamycin (mTOR), and phosphatase tensin homolog deleted on chromosome 10 (PTEN), are major regulators of inflammation, are associated with colorectal cancer, and influence the TGF-B signaling pathway." (PMID 28061442, 2017). "At the molecular levels, this coincided with the downregulation of Nfkb1, Snai1 and Stat3 mRNA, in line with our previous study showing that PA and Cer were powerful inhibitors of an IL-10-STAT3-NF-κB signaling axis regulating EMT in colorectal cancer." (PMID 35457057, 2022). "Since this study is based on inflammation-induced colorectal cancer, which typically arises from inflammation and the development of adenoma to adenocarcinoma, we attempted to evaluate effects of PEITC on NFκB1 transcription factor and three related signaling mediators and target genes." (PMID 28878142, 2017). "Differences in expression between carcinoma and normal mucosa, or differential miRNA expression by genotype, was associated with six SNPs, SMAD3 rs12708492, BMPR2 rs228545, and NFκB1 rs230510, SMAD3 rs2414937, NFκB1 rs3821958, and RUNX3 rs6672420 for colorectal cancer overall." (PMID 28061442, 2017).
Insulin resistance (870 papers, 2005 to 2026). Increased resistance towards insulin, that is, diminished effectiveness of insulin in reducing blood glucose levels. "Further, we identified Nfkb1 to be significantly correlated with Tnni3k- and Tnni3k-correlated genes involved in both, cardiac and insulin resistance-related pathways." (PMID 37628941, 2023). "Additionally, it reduces oxidative stress and inflammation through the nuclear factor kappa B subunit 1 (NFκB) signaling cascade, thereby improving insulin resistance in mice." (PMID 39021599, 2024). "Therefore, it is suggested that NFKB1, in conjunction with its cytokine-regulating function, may play a role in insulin resistance and diabetogenesis." (PMID 38003949, 2023). "Notably, IL6, NFKBIA, NFKB1, NOS3, PTPN1, PIK3R1, and STAT3 (members in the enriched WGCNA module) have been shown to alter insulin resistance." (PMID 33005175, 2020). "In agreement with previously published data, we found the increased NFKB1 mRNA level in hyperglycemic and insulin resistant patients with GDM, suggesting that this change may be related to the pathophysiology of hyperglycemia and insulin resistance that are evident in women with GDM." (PMID 33520443, 2021).
colon carcinoma (857 papers, 2003 to 2026). "We believe this work would further justify the role of NFKB1/NFKBIA axis in colon cancer susceptibility." (PMID 29564065, 2018). "In relation to NFKB1 and risk of colon cancer, the most significant single locus identified in hapConstructor was rs4648110." (PMID 21129206, 2010). "NFKB1 SNPs appeared to be important in both cancers, however the direction of risk differed with variant alleles decreasing risk of colon cancer and, other than rs230510, increasing risk of rectal cancer." (PMID 21129206, 2010). "In our study NFKB1 was found to be down-regulated, also it was connected with a proapoptotic effect in colon carcinoma cells." (PMID 27530161, 2016). "Moreover, PGE2 promotes colon tumor cell survival by upregulation of BCL2 or/and activating NFKB1 (NF-κB) in vitro." (PMID 24213116, 2011). "As activation of the NF-κB pathway promotes the formation and development of colon cancer through inducing cell proliferation, angiogenesis, and cell metastasis and inhibiting cell apoptosis, NFKB1 is employed as a potential therapeutic target for colon cancer." (PMID 39334689, 2024). "Among the upstream regulators (TFs, kinases, and MMTRs) of the DEGs, the expression of STAT3, RPS6KA5, IKBKE, ERBB2, MTOR, and NFKB1 had a positive correlation with OS in colon cancer, while the expression of CDK1, CDK5, and BRD2 had a negative correlation with OS in colon cancer." (PMID 31186640, 2019).